IFNG (interferon gamma)
Diseases named in the same sentence as IFNG in open-access papers (continued):
Sharing a sentence is not in itself a finding about the gene and the disease.
tumor (continued). "Once activated, NK cells exert tumor-suppressive effects through perforin-granzyme-mediated apoptosis, death receptor pathways, and secretion of pro-inflammatory cytokines such as interferon-gamma (IFN-γ) and tumor necrosis factor-alpha (TNF-α)." (PMID 40917849, 2025). "The major subset, Vγ9Vδ2 T cells, exhibits potent anti-tumor activity when activated, directly lysing tumor cells and secreting pro-inflammatory cytokines such as interferon gamma (IFNγ) and tumor necrosis factor alpha (TNFα)." (PMID 40075663, 2025). "Consistently, the small molecule PERK inhibitor AMG-44 reduced the immunosuppressive activity of MDSCs, promoted the expansion of tumor infiltrating CD8 + T cells expressing interferon gamma (IFNγ) and synergized with anti-PD-L1 ICI." (PMID 41372991, 2025). "Dead tumor cells release ATP, a danger signal that stimulates antigen presentation by dendritic cells, leading to the activation of IFNG‐producing T cells." (PMID 39945555, 2025). "In ascitic CD4+ T cells of tumor‐bearing mice, Tnfrsf14 knockdown resulted in a reciprocal increase in IFNγ‐producing Th1 cells and a decrease in IL4‐producing Th2 cells, whereas the levels of IL17‐producing Th17 cells remained similar." (PMID 40105652, 2025). "Expanding IFNγ-producing NKT cells in tumor tissues likely contributes to an enhanced protection of NKT cell-based anti-cancer immune therapies in multiple clinical trials." (PMID 40746558, 2025). "In our previous study, SFV/IFNγ therapy showed promising results in vivo, significantly decreasing the 4T1 tumour size in mice and enhancing T-cell infiltration into the tumour." (PMID 40547518, 2025). "We found that in the absence of the TAA-specific mAb, CD64-CR T cells produce high amounts of IFNγ, which in turn promotes the expression of PD-L1 and HLA-DR on tumor cells." (PMID 39962623, 2025). "Overall, our results indicate that monocyte infiltration can promote myeloid-CD8+ T cell crosstalk which is important for controlling IFNγ-insensitive tumours." (PMID 39746898, 2025). "The pro-inflammatory cytokines TNFα and IFNγ can improve tumor responsiveness to immune checkpoint inhibitors by enhancing T-cell infiltration and activation within the tumor." (PMID 41008842, 2025). "Beyond direct killing, CTLs secrete cytokines like interferon-γ (IFNγ) and tumor necrosis factor-α (TNFα), which further stimulate anti-tumor immunity." (PMID 40475782, 2025). "By inducing necrotic tumor cell death, radiotherapy increases the level of tumor antigens released and pro-inflammatory cytokines, such as interferon-gamma, which activate antigen-presenting cells (APCs)." (PMID 40741211, 2025). "Based on this evidence, we select CXCL10, CXCL11, and IFNG as rational proof-of-concept candidates for proposing a gene-therapeutic approach that remodels the TME by inducing tumour-intrinsic expression of immunostimulatory cytokines." (PMID 41366257, 2025). "The evaluation of interferon (IFN)γ and TGFβ gene promoter methylation showed that I2, especially in combination with chemotherapy, promoted the activation of anti-tumor genes IFNγ and silenced pro-oncogenic genes TGFβ." (PMID 39996810, 2025). "Using this approach, we aimed to reverse tumor cell resistance while increasing the sensitivity of tumor cells to Interferon gamma (IFN-γ)." (PMID 39849645, 2025). "Tumour accumulation of the radiotracer was higher when mice were treated with anti-PD-1, and further increased with IFNγ stimulation." (PMID 40265075, 2025). "Both CD8+ T cells and NK cells were found to be the primary producers of IFNγ in both WT and IFNγRKO tumours during earlier stages of tumour development (i.e. days 7–8 post-engraftment)." (PMID 39746898, 2025). "For example, interferon gamma (IFNγ) produced by activated T cells and NK cells strongly triggers PD-L1 expression in the tumor microenvironment." (PMID 39941003, 2025).
tumor (continued). "Cytotoxic CD8+ T cells recognize tumor cells’ neo-antigens and kill tumor cells, creating perforin and granzyme pores on their membrane and inducing cell apoptosis through the IFNγ and TNF pathways." (PMID 41413686, 2025). "They directly induce tumor cell apoptosis by releasing perforin and granzyme B, while concurrently secreting cytokines such as interferon-gamma(IFN-γ) and TNF-α to inhibit tumor proliferation and activate macrophages." (PMID 40977714, 2025). "The in vitro potency of CD70 TRuC T cells was assessed by measuring their tumor lytic activity and inflammatory IL-2 and interferon-gamma (IFN-γ) cytokine release response to CD70+ tumors." (PMID 40519930, 2025). "Previous studies have demonstrated that PI3K inhibition amplifies IFNγ-mediated anti-tumour responses by downregulating PD-L1, suggesting a potential combinatorial strategy for future investigations with SFV/IFNγ and anti-PD-L1." (PMID 40547518, 2025). "As such, IFNγ affects both the tumour itself and its microenvironment, with contrasting consequences on the anti-tumour response." (PMID 39746898, 2025). "IFNG treatment can enhance tumor antigen presentation and promote T cell infiltration in the TME, transforming cold tumors into hot tumors." (PMID 39945555, 2025). "This IFNγ upregulation increased MHC-I on tumor cells with minimal PD-L1 induction, resulting in an immune-responsive MHC-I/PD-L1 ratio." (PMID 41444249, 2025). "They observed that NK cells in animals treated with hypoxic tumor-derived microvesicles displayed decreased levels of CD107a, IFNγ, and GZMB compared with NK cells from animals treated with normoxic tumor-derived microvesicles." (PMID 41227342, 2025). "Incubation of human CTL expressing a transgenic TCR with antigen-presenting tumor cell spheroids induced a loss of CTL function, partially in target cell killing, almost completely in IFNg secretion." (PMID 40589546, 2025). "IL-12 acts locally on mature NK cells that constitutively express IL-12RB1/2 to rapidly induce local IFNγ production, with both immune-intrinsic and immune-extrinsic (acting on IFNγR+ infected/tumor tissues) IFNγ activity contributing to sterilizing immunity." (PMID 40410571, 2025). "On the other hand, IFNγ derived from T cells can upregulate PD‐L1 expression on the surface of tumor cells to protect tumor cells from attack by immune cells." (PMID 41357561, 2025). "In support of this finding, we observed that CD8+ T cells in MI tumours, especially those in the MI basal group, exhibited elevated IFNG expression." (PMID 41281745, 2025). "Multiple regression analysis confirmed that these cytokines, including interferon-gamma (IFN-γ), interleukin-1 receptor antagonist (IL-1ra) and VEGF, were significantly associated with tumor characteristics and treatment response." (PMID 41048959, 2025). "For example, a cyclic fasting mimicking diet reduces immunosuppressive leukocytes and enhances antitumor Th1/cytotoxic responses and IFNγ signaling in tumor leukocytes." (PMID 40145019, 2025). "Based on superior lung distribution and tumor specificity, IL‐12‐Exo effectively delayed tumor growth, while IL‐12‐exo induced IFNγ to regulate TME." (PMID 41476648, 2025). "In contrast, tumour-derived IFNγ transcriptomic signatures demonstrate superior predictive performance in on-treatment samples, with greater induction of IFNγ response genes, particularly antigen presentation genes, in responders following ICI therapy." (PMID 41291768, 2025). "The maintenance of IFNγ, IL-12(p70), and IP-10 activity suggests sustained cytotoxic and anti-tumor immunity, underscoring the potential of RS to better preserve perioperative immune competence compared with conventional surgical approaches." (PMID 41155334, 2025). "The results led to almost a two-fold upturn in intratumoral NK cells, significant tumor regression, and high interferon-gamma (IFN-γ) secretion." (PMID 40917849, 2025).
tumor (continued). "They kill tumor cells by releasing granules or inducing FasL-mediated apoptosis and release interferon-γ (IFNγ) and tumor necrosis factor α (TNFα) to induce tumor cell cytotoxicity." (PMID 40599868, 2025). "The elevated expression of IFNG in HNSCC is closely linked to the infiltration and anti-tumor activity of CD8+ T cells." (PMID 41368643, 2025). "Transcriptome signatures indicative of immune cell activation, including IFNγ, chemokine, costimulatory and tumor inflammation gene sets were all elevated in the GBM tumor after ICI treatment." (PMID 40016450, 2025). "T-lymphocytes have a direct action on cancer cells while B lymphocytes release cytokines like interferon-gamma and tumor necrosis factor-alpha which effectively neutralize tumor cells." (PMID 40740873, 2025). "Presence of interferon gamma in the tumor has been shown to accentuate immune checkpoint inhibitors." (PMID 40492845, 2025). "Key cytokines such as interleukin-6 (IL-6), tumor necrosis factor-alpha (TNF-α), interleukin-1 beta (IL-1β), and interferon-gamma (IFN-γ) are critical mediators of tumor progression, immune tolerance, and therapy resistance." (PMID 41401147, 2025). "This included PD-L1 status, CD8+ immune infiltration, TMB and expression of a ten-gene interferon-gamma (IFNγ) signature indicative of tumor inflammation." (PMID 40473950, 2025). "IFNγ serves as a key indicator of immune-mediated anti-tumor function resulting from anti-PD-1 treatment." (PMID 40873566, 2025). "In line with this, Nano-IFNγ/Zole treatment resulted in increased presentation of tumor-specific antigenic peptides to the membrane surface when the OVA was co-incubated with BMDMs." (PMID 39776793, 2025). "Senescent T cells exhibit decreased cytotoxic activity and reduced interferon-gamma (IFN-γ) production, a critical cytokine for anti-tumor immunity." (PMID 40356750, 2025). "This led to a substantial increase in intratumoral and systemic IL-1β concentrations, enhancing tumor-specific IFNγ-mediated CD8+ T cell responses." (PMID 41209313, 2025). "In parallel to promoting innate and adaptive mechanisms of host defense, IFNγ is highly involved in tumor control." (PMID 40264756, 2025). "The type II IFNγ is released at high concentrations locally at sites of a deregulated inflammation and functions as an essential element of tumor surveillance." (PMID 40287766, 2025). "Mechanistically, activated CD8+ T cells release interferon-gamma (IFN-γ), which suppresses cystine uptake in tumor cells, promoting lipid peroxidation and ferroptosis." (PMID 40636119, 2025). "In vitro experiments have shown that IFNG promotes apoptosis in the human granulosa-like tumor cell line (KGN) cells." (PMID 40083347, 2025). "NKm cells can be found in the tumor microenvironment; they secrete high levels of IFNγ, Perforin (PRF), Granulysine (GNLY), and Granzyme A and B (GZMA, GZMB) upon re-stimulation, and their impaired function is associated with cancer growth and dissemination." (PMID 41227342, 2025). "One specific example of this is the inhibition of autophagy within the tumor cell itself, leading to an increase in interferon gamma signals being produced via increased activation of the PI3K/Akt/mTOR pathway." (PMID 40429787, 2025). "In order to investigate the role of IFNG expression in tumor cells regarding ICD, we generated IFNG control and overexpressing cell lines using A549 and H1299 LUAD cell lines." (PMID 39945555, 2025). "In tumor samples, only mice treated with both dazostinag and radiation had increased levels of IFNγ on day 5, suggestive of an adaptive immune response with the combination regimen." (PMID 41296842, 2025). "In a transgenic mouse model, depletion of FAP-expressing cells led to rapid hypoxic necrosis mediated by interferon-gamma (IFN-γ) and tumour necrosis factor-alpha (TNF-α), both associated with CD8+ T cell-dependent tumour cell killing." (PMID 39780187, 2025).
tumor (continued). "IL12 enhances natural and adaptive immunity, potently stimulates the production of interferon-gamma (IFNγ) through activating NK cells and cytotoxic T cells, and alters the tumor microenvironment." (PMID 40035950, 2025). "Our study demonstrated, that TAK‐228 increases intracellular HLA‐I molecules in tumor cells, especially in the presence of IFNγ." (PMID 39258533, 2025). "Tumor tissues with a certain burden were first treated with iRFA and then injected with hydrogel containing Nano-IFNγ/Zole." (PMID 39776793, 2025). "Collectively, our study indicates that IFNG overexpression in tumor cells induces ICD, promotes DC maturation, and enhances CD8+ T cell function." (PMID 39945555, 2025). "The percentage of NK cells and interferon-gamma-expressing NK cells within tumor-infiltrating leukocytes were also significantly decreased in sMIC expressing Lewis lung carcinoma implants." (PMID 40849493, 2025). "Mutations in ERβ lead to increased infiltration of T cells and neutrophils in the TME 63, along with decreased interferon gamma (IFN-γ) levels, which promote tumor growth and progression." (PMID 40303343, 2025). "Together, these data suggest that the induction of LMP7 expression by IFNγ, potentially derived in vivo from tumor-residing CD8+ T cells, establishes an intrinsic dependency of TNBC/IBC cells on LMP7 function." (PMID 40507366, 2025). "Interferon-gamma (IFN-γ) is a critical cytokine that modulates the tumor-promoting or tumor-suppressing behavior of BMSCs in the cellular matrix." (PMID 40181963, 2025). "On the one hand, CD8+T cells can inhibit the proliferation of tumor cells and enhance immune activity through IFNγ secretion." (PMID 41357561, 2025). "Both cytotoxic subsets secrete substantial amounts of the anti-tumor cytokines interferon-gamma (IFN-γ) and tumor necrosis factor-alpha (TNFα), contributing to their tumor-suppressive functions." (PMID 40361239, 2025). "While RT induces inflammation and recruits activated tumor-infiltrating lymphocytes (TILs), including cytotoxic T lymphocytes (CTLs), the resulting radiation- and IFNγ-dependent PD-L1 expression restores an immunosuppressed tumor microenvironment." (PMID 39941761, 2025). "Serum interferon-gamma (IFN-γ) levels positively correlated with intrahepatic tumor size (r = 0.199, p<0.05)." (PMID 40568585, 2025). "The pharmacodynamic data in this study additionally highlight the dual role of the IFNγ-PD-L1 axis in tumor immunity." (PMID 40515479, 2025). "The antigen specific anti-tumor functions of CAR T cells are typically measured against the production of IFNγ and CD107a degranulation assays." (PMID 40416968, 2025). "Both type I (IFNα and IFNβ) and type II IFNs (IFNγ) are involved in anti-viral immune responses; however, they can also protect against tumor proliferation." (PMID 39857692, 2025). "Fc-enhanced 9D9 also induced higher levels of endothelial PD-L1, as compared to Fc-null and parental 9D9 mAbs, revealing increased exposure of tumor endothelial cells to IFNγ." (PMID 40460830, 2025). "In UM, elevated IDO expression has not been directly correlated with metastatic burden but is associated with increased immune cell infiltration and elevated levels of interferon-gamma (IFN-γ) within the tumor microenvironment." (PMID 40725830, 2025). "Conversely, IFNG score, Merck18, myeloid-derived suppressor cells (MDSCs), CD8, and tumor-associated M2 macrophages are higher in the low NETs signature group." (PMID 40988926, 2025). "In 4T1 tumours treated with SFV/IFNγ and TLR2/1 ligand Pam3SCK4, the amount of CTLs was increased and the amount of Tregs was significantly reduced." (PMID 40547518, 2025). "CD8+ T cells play a crucial role in tumor elimination by directly killing tumor cells and increasing local IFNγ levels, which promote tumor-suppressing Th1 responses." (PMID 39851516, 2025).
tumor (continued). "This “delay” in peak IFNγ suggested a period of recovery from ex vivo culture for T cell activation and engagement in anti-tumor activities in response to anti-PD-1 treatment." (PMID 40873566, 2025). "Lymphocytes inhibit apoptosis by secreting TNF alpha and interferon gamma and contribute to long-term survival by preventing tumor migration and invasion." (PMID 40282930, 2025). "NK cells as an important component of the anti-tumor immune response, exert anti-tumor immune functions through the secretion of cytokines such as IFNγ and TNFα." (PMID 40356913, 2025). "This construct promoted immune cell infiltration, stimulated interferon-gamma (IFN-γ) production, and significantly improved tumor control and survival in CRC models." (PMID 40507337, 2025). "CD8+ T cells promote ferroptosis in tumor cells by secreting interferon-gamma (IFN-γ), which suppresses SLC7A11 and impairs cystine uptake." (PMID 40650229, 2025). "We also assessed phagocytosis of tumor cells by flow cytomtery by macrophages that were polarized to M1 or M2 with either IFNγ or IL-10 respectively." (PMID 40078999, 2025). "We found that IFNG expression in the tumor environment correlated with the proportion of CD8 + TILs, even when excluding EBV-positive cases." (PMID 39722065, 2025). "Subsequent T-cell activation assays demonstrated that stimulation with the CD3 monoclonal antibody effectively induced robust T-cell activation and perfectly capable of killing tumor cells, accompanied by significant secretion of interferon-gamma (IFN-γ)." (PMID 41427134, 2025). "To test these possibilities, we stimulated treatment-naïve tumours ex vivo with isotype control, anti-PD-L1 antibodies, or recombinant IFNγ." (PMID 40523200, 2025). "Our study demonstrates that increased intracellular IFNG in tumor cells can induce ICD, thereby promoting ATP release." (PMID 39945555, 2025). "Using anti-IFNγ antibodies, anti-TNF antibodies, and CRISPR technology, the researchers confirmed IFNγ as the primary mediator of tumor cell ferroptosis." (PMID 40064873, 2025). "Recent studies have investigated the combination of TTF with the immune checkpoint inhibitor anti-PD1, which resulted in tumor shrinkage and increased infiltration of IFNγ+ T cells in mouse models." (PMID 40075663, 2025). "Interferon gamma serves as a chemoattractant to leukocytes facilitating the invasion into the tumor microenvironment." (PMID 40429787, 2025). "According to research studies, Interferon gamma inhibits tumor cell growth and promotes tumor cell apoptosis." (PMID 41346580, 2025). "It has been reported that inflammatory cytokines, particularly IFNγ, can upregulate the expression of PD-L1 in tumor cells, ultimately resulting in tumor immunosuppression." (PMID 38338893, 2024). "But combination Ad-E and αPD-1 mAb with antibiotics treatment significantly decreased the level of CD3+ T cells, NK cells, IFNγ+CD8+ T cells in tumor tissue." (PMID 39251538, 2024). "It is possible that pembrolizumab has not produced a stronger change because this set of tumors happened to be immunologically ‘cold’, as evidenced by IFNγ levels below the lower limit of detection across all tumor samples." (PMID 38892347, 2024). "Upon dissociating the tumors to analyze both TILs and tumor cells, we found that most of the attIL12-TILs in the tumor microenvironment produced high levels of IFNγ." (PMID 39574893, 2024). "In the T cells generated via PBNP‐PTT, both CD8+ effector T cells (39.2 ± 2.1%) and effector memory T cells (14.8 ± 6.6%) produced IFNγ and TNFα in response to target U87 cells, suggesting tumor‐specific activation." (PMID 38818122, 2024). "Tumoral PD-L1 expression can be endogenously induced by oncogenic signaling or PD-L1 gene alterations in tumor cells or adaptively by IFNγ secreted from tumor-infiltrating immune cells in the TME." (PMID 38729997, 2024). "Interferon gamma (IFNγ) is a critical cytokine known for its diverse roles in immune regulation, inflammation, and tumor surveillance." (PMID 38418901, 2024).